DKK2 (dickkopf Wnt signaling pathway inhibitor 2)
Diseases named in the same sentence as DKK2 in open-access papers (continued):
Sharing a sentence is not in itself a finding about the gene and the disease.
cancer (34 papers, 2007 to 2025). A tumor composed of atypical neoplastic, often pleomorphic cells that invade other tissues. "Glycolysis in Lgr5 expressing cancer cells was reduced along with the loss of LYZ+ cells by Dkk2 knockout." (PMID 38659853, 2024). "To analyze the consequence of the loss of LYZ+ cells by Dkk2 knockout in cancer stem cell niche formation, we enriched Lgr5 positive cells that consist of stem cells, stem cell niche cells and transit amplifying cells in the homeostatic condition." (PMID 38659853, 2024). "Considering the activity of Dkk2 and -4, it is interesting to note that only Dkk1 has been implicated thus far in cancer-associated bone lesions." (PMID 17971207, 2007). "Splenic injection of Dkk2-knockout (KO) cancer organoids into C57BL/6 mice resulted in a significant reduction of liver metastases." (PMID 38659853, 2024). "In the liver metastatic foci, DKK2 knockout rescued HNF4A protein levels followed by reduction of lysozyme positive cancer cells." (PMID 38659853, 2024). "The percentile of LYZ+ cells in total cancer cells was decreased about threefold in Dkk2 knockout metastasized cells (KO) compared to the AKP control cells in liver." (PMID 39535280, 2024). "We have shown that DKK2 is required for the formation of LYZ+ cancer cells carrying Paneth cell properties." (PMID 38659853, 2024). "The percentile of LYZ+ cells in total cancer cells was decreased about 3-fold in Dkk2 knockout metastasized cells (KO) compared to the AKP control cells in liver." (PMID 38659853, 2024). "DKK1 and DKK2 epigenetic silencing through promoter methylation have been observed in multiple cancers, including colorectal cancer, breast cancer, Ewing sarcoma, and gastric cancer." (PMID 37551167, 2022). "Those investigations have revealed some potential links of DKK2 with cellular function to tumorigenesis which is very important for us to further understand how this protein contributes to cancer pathology." (PMID 31583260, 2019). "Though in most cases DKK2 acts as an antagonist of the Wnt signaling pathway, it is considered as an oncogene in a large portion of cancer types and so does is in our study." (PMID 31583260, 2019). "The biochemical characterization of DKK2 would facilitate detailed analyses of its role in Wnt signaling and dysregulation into ischemic vascular diseases, and cancer." (PMID 31212691, 2019). "In order to translate the observed findings to human cancer biology we integrated our signature of differentially regulated genes in dependence of Dkk2 knock out with authentic human tumors." (PMID 25826080, 2016). "RUNX2 further affects cancer cell invasion and osteolysis, which seems also true for ES as demonstrated by us in the context of DKK2." (PMID 27363011, 2016). "Dkk2 a antagonist of the Wnt/β-catenin-signaling pathway was shown to be silenced in diverse cancers." (PMID 25826080, 2016). "In renal carcinoma, DKK1 and DKK2 expression is epigenetically suppressed, and their ectopic expression induces apoptosis, and decreases invasion, of cancer cells." (PMID 24091497, 2014). "Furthermore, Paneth cells generate a stem cell niche for cancer and are regulated by the DKK2 gene during cancer metastasis." (PMID 40665579, 2025). "Conversely, in cancer studies DKK2 generally inhibits Wnt signaling." (PMID 36599670, 2023). "Furthermore, cancer cell-secreted DKK2 suppresses immune cell activation via an unconventional Wnt-unrelated pathway." (PMID 36599670, 2023). "More recently, DKK2 has been identified as a novel oncogene in various cancer types." (PMID 31583260, 2019). "As a member of the dickkopf family, the role of DKK2 varies depending on the cancer type." (PMID 31583260, 2019). "In addition, the expression of DKK2 in PDAC is the highest among almost all kinds of cancer types based on TCGA data." (PMID 31583260, 2019).
cancer (continued). "Whereas DNA methylation levels of DKK2 of normal crypts from regions adjacent to the cancer and distal region were significantly higher on the right side than the left side of the colon, that from the proximal region was significantly higher on the left side of the colon than the right side." (PMID 28533824, 2017). "DKK2, a putative Wnt signaling inhibitor, is generally down-regulated in human cancers." (PMID 27901495, 2017). "In many of these cancers DKK2 was down regulated due to promoter methylation." (PMID 25826080, 2016). "Thus, the availability of recombinant DKK2 would facilitate the understanding of its regulation and dysregulation in ischemic vascular diseases, and angiogenesis-dependent tumor growth and metastasis contributing to the treatment of cancer." (PMID 31212691, 2019). "Expression of DKK1, DKK2, and SFRP1 was verified by IHC staining of clinical specimens of colon normal epithelium, adenomatous, and cancer tissues." (PMID 38334454, 2024). "Dickkopf 2 (DKK2), an inhibiting factor of the Wnt pathway, is reported to be a crucial regulator in multiple cancers." (PMID 34364402, 2021). "Wnt pathway modulator Dickkopf 2 (Dkk2) and signaling of the G protein-coupled estrogen receptor (GPER) seem to have essential functions in numerous cancer types." (PMID 33679613, 2021). "We examined DNA methylation levels of SFRP1, SFRP2, SFRP5, DKK2, DKK3, mir34b/c, RASSF1A, IGFBP7, CDKN2A, and MLH1 in cancerous glands and normal crypts isolated from cancer tissue and the surrounding normal mucosa." (PMID 28533824, 2017). "Compared to surrounding normal colonic crypts, the methylation levels of SFRP1, SFRP2, SFRP5, DKK2, DKK3, mir34b/c, and RASSF1A in MSS CRCs were significantly higher in cancer crypts." (PMID 28533824, 2017). "We examined the DNA methylation levels of SFRP1, SFRP2, SFRP5, DKK2, DKK3, mir34b/c, RASSF1A, IGFBP7, CDKN2A, and MLH1 in normal colonic crypts isolated from regions that were adjacent to the cancer, as well as distal and proximal regions (left and right sides)." (PMID 28533824, 2017).
infection (2 papers, 2014 to 2024). The state of being infected such as from the introduction of a foreign agent such as serum, vaccine, antigenic substance or organism. "CYP1B1-AS1 was upregulated in both Cb and Cb NMII dotA::Tn (CbA) infections, while lnc-DKK2 was specifically downregulated in Cb infection." (PMID 39711545, 2024). "In conclusion, our study employed a global comparative multi-infection model approach, which was instrumental in identifying CYP1B1-AS1 and lnc-DKK2 as potential lncRNA signatures specific to Cb infection." (PMID 39711545, 2024).
myopathy (1 paper, 2023). A disease of the muscle in which the muscle fibers do not function properly. "Furthermore, RNA-seq data showed alterations in several genes involved in Wnt signaling, such as APC, DACT1, DKK2, DVL2, and WNT4, emphasizing an important role for Wnt signaling in WB myopathy." (PMID 38130476, 2023).
retinopathy (1 paper, 2014). "We further observed that DKK1 diminished retinal vessel density and increased avascular area in an in vivo murine model of oxygen-induced retinopathy, whereas DKK2 showed opposite results." (PMID 24091497, 2014). "To further investigate potential DKK1 and DKK2 involvement in pathological angiogenesis, we applied an oxygen-induced retinopathy (OIR) model to DKK1 Tg and DKK2 Tg mice." (PMID 24091497, 2014).
DKK2 also shares sentences with these, for which no sentence is quoted: gastrointestinal tumors (3 papers); Myocardial fibrosis (3); metastatic tumor (2); Oral Squamous Cell Carcinoma (2); Alzheimer disease (1); cervical neoplasms (1); cleft palate (1); cylindroma (1); diabetes (1); hematological neoplasms (1); hematopoietic neoplasms (1); Hypertension (1); infantile hemangioma (1); leukemia (1); liver (1); liver fibrosis (1); myeloma (1); osteoarthritis (1); pituitary tumor (1); sarcopenia (1); Sepsis (1); skin cancer (1); spiradenoma (1); squamous intraepithelial lesions (1).